LGALS3 (galectin 3)
Diseases named in the same sentence as LGALS3 in open-access papers (continued):
Sharing a sentence is not in itself a finding about the gene and the disease.
breast carcinoma (continued). "In particular, smoking promotes chemotherapy-resistant and anti-apoptotic effects on breast cancer cells by signaling cascades of STAT3, galectin-3, and nicotine acetylcholine receptors." (PMID 34796198, 2021). "They found that LGALS3BP secreted by the human metastatic breast cancer cells MDA-MB-231 inhibited monocyte-derived fibrocyte differentiation, and, conversely, galectin-3 promoted monocyte-derived fibrocyte differentiation." (PMID 34565385, 2021). "After further adjustment for age at breast cancer diagnosis, ethnicity, and receipt of trastuzumab, associations between the receipt of anthracycline and NT-proBNP values persisted (p < 0.001), while associations with sST2 and galectin-3 remained non-significant." (PMID 34362097, 2021). "It was next demonstrated that a restoration of TRAIL-induced cell death by galectin-3 in BT459 cells required its phosphorylation on serine-6 and that TRAIL sensitivity may be influenced by a sequence polymorphism commonly found in galectin-3 and associated with breast cancer incidence." (PMID 29498673, 2018). "Cleaved galectin-3 co-localized with active MMP-2/MMP-9 in mouse xenograft and human breast cancer tissues, indicating that cleavage of galectin-3 after alanine 62 is attributable to enzymatic activities of MMPs." (PMID 23625538, 2013). "Recent reports have shown that peptides corresponding to galectin-3 fragments formed by MMP cleavage that contained the CRD but which were longer than Gal-3C increased tumor growth and angiogenesis in breast cancer xenograft models." (PMID 21765917, 2011). "Comparable to PDAC cells (PancTuI), esophageal adenocarcinoma OE-33 cell line, the UM-UC-3 bladder cancer cell line, non-small cell lung adenocarcinoma NCI-H1693 cells, breast cancer cells (MCF-7, MDA-MB-231) and ovarian cancer cells (OVCAR-3, BG-1 and SKOV-3) expressed intracellular galectin-3." (PMID 38259448, 2023). "Galectin-3 protein expression was much higher in breast tumor tissues relative to precancerous tissue, and triple-negative breast tumors have significantly higher levels of galectin-3 expression than other subtypes of breast cancer." (PMID 38202898, 2023). "Studies in colorectal and breast cancer have described an increase in growth factors and cytokines in the TME after platelet extravasation into the tumors, and this has been predicted due to GPVI–galectin-3 interaction." (PMID 34290095, 2021). "sST2 and galectin-3 do not appear to differentiate between anthracycline recipients and non-recipients amongst breast cancer survivors." (PMID 34362097, 2021). "Additionally, studies showed that galectin-3 binds to β-catenin and TCF4 and then activates wnt signaling targets genes such as cyclin D1 and c-Myc in breast cancer cells." (PMID 28146425, 2017). "JIMT-1 breast cancer cells were pre-treated with the proposed inhibitor for 24 h, then treated with 0.3 mm GPN for 12 min to disrupt lysosomes, and then fixed and stained for galectin-3." (PMID 27129206, 2016). "Previous works had shown that human breast carcinoma cells expressing galectin-3, unlike its galectin-3 null parental cells, progressively grew and metastasized when inoculated into the mammary fat pad of athymic nude mice." (PMID 24982845, 2014). "Circulating serum galectin-3 may increase through MMP9-dependent cleavage of membrane-bound galectin-3, and this cleavage of galectin-3 by MMP9 promotes breast cancer angiogenesis and progression." (PMID 25499743, 2014). "To test whether galectin-3 secreted into the culture medium was related to ECM1 action, we treated cultured breast cancer cells with rhECM1." (PMID 25499743, 2014). "In breast cancer tissues, galectin-3 but not Beclin1 was highly expressed in cancer compared to normal tissue." (PMID 22039439, 2011). "Furthermore, another breast cancer study demonstrated that there was no change in galectin-3 levels in response to doxorubicin." (PMID 38539500, 2024).
breast carcinoma (continued). "In a mouse model of TN breast cancer, treatment with AC and ICRP reduced tumor volume, prolonged survival, increased the numbers of infiltrating and systemic CD8+ T cells, and decreased the numbers of tumor suppressor molecules such as galectin-3, PD-L1, and IL-10." (PMID 34638242, 2021). "The absence of a difference in galectin-3 levels between anthracycline recipients and non-recipients suggests that galectin-3 is likely not a useful biomarker of cardiotoxicity after anthracycline receipt for breast cancer." (PMID 34362097, 2021). "However, Cox regression analysis showed that galectin-3 expression was not an independent prognostic factor for breast cancer." (PMID 25254965, 2014). "In this subanalysis of the CECCY trial, we concluded that carvedilol did not change galectin-3 and MPO blood levels after ANT chemotherapy in women with breast cancer." (PMID 35087624, 2022).
Myocardial fibrosis (146 papers, 2012 to 2026). "The molecules TGF-β1, TNF-α, IL-6, galectin-3, and galectin-1 are critically involved in the cardiac inflammatory and profibrotic cascade, and they have been linked to myocardial fibrosis severity and to structural and electrical atrial remodeling." (PMID 41590667, 2026). "This pattern suggests a potential association between galectin-3 and ischaemic or vascular inflammatory processes, in addition to myocardial fibrosis." (PMID 41158187, 2025). "Bearing in mind the role of galectin-3 in myocardial fibrosis, future analysis of cardiovascular risk in patients with severe OSA should be considered." (PMID 39941305, 2025). "Galectin-3 has been implicated in myocardial fibrosis through the activation of fibroblasts and the promotion of TGF-β signaling, contributing to atrial stiffening and electrical heterogeneity." (PMID 40710785, 2025). "Emerging biomarkers like IL-32, Dickkopf-related protein 1 (DKK-1), and galectin-3 also show potential in further refining risk assessment, particularly for atherosclerosis and myocardial fibrosis in rheumatic diseases." (PMID 40937212, 2025). "Galectin 3 (Gal‐3) is a galactoside‐binding protein involved in cell–cell and cell–matrix interactions, and implicated in atherosclerosis, myocardial fibrosis and HF." (PMID 39822053, 2025). "Galectin 3 is associated with inflammatory processes and myocardial fibrosis, being found to be present at the myocardial level after the onset of ischemia." (PMID 38541144, 2024). "Prolonged galectin-3 expression is associated with increased activation of fibroblasts into matrix-producing fibroblasts, contributing to the development of myocardial fibrosis." (PMID 38054039, 2023). "Natriuretic peptides are relevant for diagnosis and prognosis in HF patients, and biomarkers of myocardial injury (cTnI) and myocardial fibrosis (Galectin-3 and ST2) are used for risk stratification." (PMID 35780161, 2022). "In the later phase of ACS, galectin-3 enhances the transition from acute to chronic inflammatory condition and causes myocardial fibrosis, leading to unfavourable ventricular remodelling." (PMID 35053194, 2021). "Galectin-3, a β-galactoside-binding lectin, is a protein that has recently been heavily implicated in the pathophysiology of myocardial fibrosis." (PMID 31885743, 2019). "With a galectin-3 cutoff value of 12.3 ng/ml (the highest quartile of galectin-3) for detecting the presence of myocardial fibrosis, a Qa >2 L/min increased the risk for myocardial fibrosis by 9.6-fold with this cutoff value (odds ratio = 2.97–31.23, p < 0.001)." (PMID 35966517, 2022). "Moreover, mice genetically deficient in Galectin-3 display less myocardial fibrosis at chronic infection." (PMID 34867990, 2021). "In addition to evaluating the potential role of circulating galectin-3 concentration as cardiac diagnostic biomarkers, further research is needed to assess myocardial fibrosis and galectin-3 expression in the heart tissues of dogs with heart diseases." (PMID 34722704, 2021). "Soluble suppression of tumorigenicity 2 (sST2), galectin-3 (Gal-3) and the N-terminal portion of the B-type natriuretic peptide (NT-proBNP) have been related to cellular death, myocardial fibrosis, inflammation and congestion." (PMID 40429491, 2025). "Galectin-3, secreted by activated macrophages, mediates inflammatory processes and tissue remodeling, particularly by promoting myocardial fibrosis and increasing cardiac stiffness and dysfunction." (PMID 40699731, 2025). "Galectin-3, a macrophage-derived lectin involved in myocardial fibrosis and inflammation, contributes to LV remodelling and progressive cardiac dysfunction." (PMID 41158187, 2025). "Galectin-3 is known to reflect myocardial fibrosis and remodeling—key pathophysiological processes in DBCM—and has shown prognostic associations with both systolic/diastolic dysfunction and cardiovascular outcomes among individuals with T2DM." (PMID 41007876, 2025).
Myocardial fibrosis (continued). "Galectin-3 has been examined as a potential marker for myocardial fibrosis in felines diagnosed with HCM." (PMID 40217634, 2025). "Biomarker profiles in marathon runners revealed elevations in Galectin-3, PIIINP, and sVCAM-1—markers associated with myocardial fibrosis and endothelial stress." (PMID 40710785, 2025). "Inflammatory factors include tumor necrosis factor (TNF), galectin-3 (gal-3), nuclear factor kappa-B (NF-κB) and interleukin (IL), which act on effector cells and promote myocardial fibrosis through multiple pathways." (PMID 40881586, 2025). "Galectin-3 is a β-galactoside-binding lectin that plays a key role in myocardial fibrosis and inflammatory processes." (PMID 40918185, 2025). "Galectin-3 is a β-galactoside-binding lectin that promotes myocardial fibrosis by stimulating macrophages and cardiac fibroblasts." (PMID 40937212, 2025). "Combined with the analysis of the results of this study, the increased level of galectin-3 promotes the process of myocardial fibrosis, affects atrial function, and indirectly promotes the formation of left atrial appendage thrombosis." (PMID 39139162, 2024). "Galectin-3 (Gal-3) is a β-galactosidase binding lectin that plays a role in myocardial fibrosis and proliferation." (PMID 38507154, 2024). "In a pre-clinical setting, galectin-3 inhibition results in a reduction in myocardial fibrosis and improvement of LV function; however, to date, its favorable effects are difficult to demonstrate in patients." (PMID 36979345, 2023). "Galectin-3 plays a central role in promoting myofibroblast proliferation, which leads to tissue remodeling and myocardial fibrosis." (PMID 36673621, 2023). "For all patients, we performed CMR, speckle tracking echocardiography (STE), and biomarker assessment for HFpEF (NT-proBNP), for myocardial fibrosis (Galectin-3), and for endothelial dysfunction [ADAMTS13, von Willebrand factor, and their ratio]." (PMID 37297827, 2023). "Galectin 3 (Gal-3) is released by activated cardiac macrophages and can be involved in key processes such as myocardial fibrosis and cardiac remodeling." (PMID 37644795, 2023). "Galectin 3 is actively involved in myocardial fibrosis-inducing fibroblast proliferation and collagen deposition, mainly studied in animal models." (PMID 35727504, 2023). "In galectin-3 (Gal-3) KO hypertensive model mice, spleen Tregs significantly increased, and cardiac inflammation and myocardial fibrosis were improved." (PMID 36911741, 2023). "Increased serum galectin-3 levels activate a variety of profibrotic factors and induce cardiac fibroblasts to proliferate and transform, contributing to myocardial fibrosis and adverse remodeling." (PMID 34979958, 2022). "Myocardial fibrosis and expression of galectin-3, pro-collagen 1-α and MMP-9 were increased after treatment with all ICIs." (PMID 36158826, 2022). "In a rabbit HFrEF model, CCM therapy reduced cardiac expression of connective tissue growth factor and galectin-3 (a pro-fibrotic marker involved in myocardial structural remodeling) with a reduction of myocardial fibrosis." (PMID 36233734, 2022). "Then, we demonstrate that a high-flow AVF can be a significant determinant of myocardial fibrosis, which is shown as a discretely increased native T1 value coupled with an increase in the validated biomarker galectin-3." (PMID 35966517, 2022). "Soluble suppression of tumorigenesis-2 (sST2) and galectin-3 (Gal-3) are two biomarkers of fibrogenesis and inflammation, as well as of their interactions, thought to reflect myocardial fibrosis." (PMID 35277168, 2022). "Galectin-3 reflects the intensity of myocardial fibrosis and cardiac biomechanical stress, microvascular inflammation, oxidative stress and vascular osteogenesis in atherosclerosis." (PMID 35455719, 2022).
Myocardial fibrosis (continued). "Serum galectin-3 levels correlated very well with native T1 relaxation times, both global (r = 0.378, p = 0.019) and septal T1 values (r = 0.421, p = 0.009), suggesting the usefulness of galectin-3 for estimating myocardial fibrosis." (PMID 35966517, 2022). "Hemodialysis patients showed significantly higher galectin-3 value and increased T1 relaxation time compared to healthy volunteers, suggesting increased myocardial fibrosis in uremic cardiomyopathy." (PMID 35966517, 2022). "Galectin-3 has been shown to play a role in the pathophysiology of heart failure (HF) by promoting myocardial fibrosis and inflammation and has become a significant predictor of HF." (PMID 34979958, 2022). "In this study, the degree of myocardial fibrosis was assessed with non-contrast cardiac MRI–derived native T1 relaxation time and an emerging myocardial fibrosis biomarker, galectin-3." (PMID 35966517, 2022). "Galectin-3 influences the development of myocardial fibrosis through an effect on the important intermediates of that regulation: phosphatase and tensin homolog (PTEN) and protein tyrosine kinase 2 (PTK2)." (PMID 35053194, 2021). "Galectin-3, exogenously added, is closely related to myocardial fibrosis and is strongly expressed in cardiac myofibroblasts, which can be used as an independent predictor of myocardial fibrosis." (PMID 35053194, 2021). "Aldosterone, another RAAS inhibitor, was not prescribed to any of the patients, but its effect on reducing galectin-3 levels and its effect on myocardial fibrosis has been documented." (PMID 34830647, 2021). "It has also been reported that serum HE4 levels are elevated in patients with left heart failure and right heart failure and exhibit a significant correlation with galectin-3, a biomarker of myocardial fibrosis." (PMID 34674652, 2021). "Galectin-3 exerts an effect promoting the myocardial fibrosis process, while miR-214 can regulate fibroblast proliferation." (PMID 35053194, 2021). "In animal models, the extent of myocardial fibrosis following myocardial infarction is well correlated with both myocardial and serum galectin-3 levels, and expression of myocardial galectin-3 was significantly increased." (PMID 34830647, 2021). "Cardiomyocyte-secreted galectin 3 (Gal-3), which is a member of the β-galactoside-binding protein family, has been reported to mediate cardiac fibroblast activation and promote myocardial fibrosis." (PMID 34007848, 2021). "One study assessing the myocardial fibrosis by histopathology and Galectin-3 concentration found that the degree of fibrosis in dogs with MMVD was higher than in control group." (PMID 34643161, 2021). "In our study, myocardial fibrosis was observed in only one patient in cardiac magnetic resonance but, according to the literature, galectin-3 is a marker of early damage before fibrosis appears." (PMID 33801193, 2021). "In the experimental part of the work on animals, Yoshio Takemoto demonstrated the pathogenetic mechanisms of the effect of galectin-3 on the development of myocardial fibrosis and the induction of AF." (PMID 32784491, 2020). "Increasing evidence showed that circulating galectin-3, an emerging biomarker of myocardial fibrosis, immune activation, and enhanced inflammation, has been involved in the pathogenesis of many cardiovascular diseases." (PMID 32893848, 2020). "Perindropil and modified citrus pectin (MCP) are correlated to the inhibition of myocardial fibrosis by acting on the myocardial Galectin-3 (Gal-3) gene." (PMID 33409282, 2020). "The results from the same research group further suggested that levels of galectin-3 correlated significantly with the degree of myocardial fibrosis." (PMID 31885743, 2019). "The galectin-3 positive cell number increased slightly at 48 hours and was followed by myocardial fibrosis." (PMID 30673749, 2019).